NRP1 (neuropilin 1)
Diseases named in the same sentence as NRP1 in open-access papers (continued):
Sharing a sentence is not in itself a finding about the gene and the disease.
lymphatic malformation (2 papers, 2020 to 2024). Primary lymphedema is caused by anatomic or functional defects in the lymphatic system, resulting in chronic swelling of body parts and lymphatic-system malformation. "This study focuses on identifying rare variants in the NRP1 and NRP2 genes that could be linked to the development of lymphatic malformations in patients diagnosed with lymphedema." (PMID 33212964, 2020).
monocytic leukemia (2 papers, 2020 to 2023). "Human THP1 monocytic leukemia cells that were treated with phorbol 12-myristate 13-acetate (PMA) also expressed NRP-1, shown via the use of an anti-hNRP-1 mAb, and also bound Nb1, Nb2, Nb3, Nb4, Nb6, Nb7 and Nb8." (PMID 33266104, 2020). "Two of the three NRP‐1/CD304‐positive AML cases had monocytic differentiation and were diagnosed as acute monoblastic and monocytic leukemia." (PMID 36965095, 2023).
ovarian adenocarcinoma (2 papers, 2008 to 2020). An adenocarcinoma that arises from the ovary. "A low NRP1 protein expression was also confirmed in UWB and UWB-BRCA cells, derived from serous OC, whilst SKOV3 cells, derived from the ascites of an ovarian adenocarcinoma patient, showed a high basal expression of NRP1 protein (5 fold, with respect to UWB cells)." (PMID 31898520, 2020).
preeclampsia (2 papers, 2021 to 2025). Preeclampsia is a hypertensive disorder of pregnancy that is characterized by new-onset hypertension with proteinuria presenting after 20 weeks of gestation, and depending on mild or severe forms may initially present with severe headache, visual disturbances, and hyperreflexia. "Studies on tissue NRP-1 expression on placental pathology have focused on decreased expression of NRP-1 in the syncytiotrophoblast villous layer in preeclampsia." (PMID 40507480, 2025).
radicular cyst (2 papers, 2021 to 2023). "Furthermore, 1-nonadecene significantly upregulated the gene expression of ACE-2, NRP-1, and TMPRSS2, indicating a possible higher viral load in radicular cysts compared to other periapical lesions but less than the healthy control." (PMID 34749700, 2021).
rheumatoid arthritis (2 papers, 2021 to 2024). A chronic, systemic autoimmune disorder characterized by inflammation in the synovial membranes and articular surfaces. "Further, Nrp1 activation by another Semaphorin 3 protein (Sema3B) has been found to promote pro-resolving polarization in macrophages from rheumatoid arthritis patients." (PMID 39234267, 2024). "This suggests an anti-inflammatory role of NRP1, which has also been highlighted in a model of rheumatoid arthritis via the SEMA 3A/NRP1 signaling pathway." (PMID 34277411, 2021).
skin papilloma (2 papers, 2022 to 2026). A benign papillary neoplastic growth on the skin composed of epithelial cells and a fibrous stalk. "After 25 weeks of treatment, all control mice developed skin papillomas, but none of the Nrp1 deficient mice developed a neoplasm." (PMID 36203599, 2022).
spinal cord injuries (2 papers, 2021 to 2022). "Another study showed that galectin-1 interacts with the Neuropilin-1/PlexinA4 receptor complex in damaged neurons to contribute to axonal regeneration and locomotor recovery after spinal cord injury." (PMID 36008956, 2022). "Blocking NRP-1 leads to inhibited axonal pruning of compensatory neural circuits within the CNS further highlighting the critical role of NRP-1 in cellular signaling and its role in the recovery of motor function after spinal cord injuries." (PMID 33395426, 2021).
Splenomegaly (2 papers, 2013 to 2022). Abnormal increased size of the spleen. "This is further supported by the level of NRP1+PD‐1+ conventional Th cells in male BXSB.Yaa, which is strongly correlated with systemic autoimmunity as indicated by splenomegaly and autoantibody production." (PMID 36069030, 2022). "Transfer of NRP1+PD‐1+ Foxp3− Th cell elicited disease progression in protected male BXSB.Yaa Nr4a2 cKO mice, with splenomegaly and increases in serum antibodies, including ANA." (PMID 36069030, 2022).
tongue squamous cell carcinoma (2 papers, 2012 to 2014). A squamous cell carcinoma that arises from the tongue. "In our previous studies, we found that neuropilin-1 (NRP1) is overexpressed in tongue squamous cell carcinoma and that this overexpression is associated with cell migration and invasion." (PMID 24999732, 2014). "In our previous studies, we found that NRP-1 is significantly overexpressed in tongue squamous cell carcinoma (TSCC) tissues, compared with normal non-cancerous controls." (PMID 24999732, 2014).
ventricular septal defect (2 papers, 2012 to 2014). The presence of a defect (opening) in the septum that separates the two ventricles of the heart. "All Tie2Cre/Nrp1 mutants also had a ventricular septal defect, which is a hemodynamic necessity of a common arterial trunk." (PMID 22396765, 2012).
acute cholecystitis (1 paper, 2020). "We examined NRP‐1 expression in 91 GBC samples and in 120 cholecystitis tissues (60 acute cholecystitis and 60 chronic cholecystitis) using immunohistochemistry (IHC)." (PMID 32951327, 2020).
adenovirus infection (1 paper, 2019). "We also used a rat epicardial cell line to investigate potential downstream targets of NRP1 and found that downregulating the expression of NRP1 via small hairpin (sh)RNA adenovirus infection, led to a decrease in β-catenin expression, which is an important regulator of EMT." (PMID 31167777, 2019).
age-related hearing loss (1 paper, 2017). "Neuropilin-1 (Nrp1) encodes the transmembrane cellular receptor neuropilin-1, which is associated with cardiovascular and neuronal development and was within the peak SNP interval on chromosome 8 in our prior GWAS study on age-related hearing loss (ARHL) in mice." (PMID 29059194, 2017).
AIDS (1 paper, 2017). A syndrome resulting from the acquired deficiency of cellular immunity caused by the human immunodeficiency virus (HIV). "The specific SNPs associated with having multiple AIDs were neuropilin 1 (NRP1, rs2666236), RGS1 (rs2816316), CD69 (rs4763879), and FUT2 (601338)." (PMID 29182645, 2017).
alcohol (1 paper, 2022). "Moreover, dependent inhibition of NRP1 targeted HSCs and ameliorated alcohol-induced steatohepatitis by decreasing hepatic lipid droplets as well as inflammation through regulation of the IGFBP3 and SERPINA1A12 signaling pathways." (PMID 36077090, 2022).
anaplastic astrocytoma (1 paper, 2021). "In detail, one patient collected tumor specimens in all stages of MT in the present cohort.PRKCQ,PPIF,NRP1,MEFV,GGT1,FAN1, andBTKmutations were found in both DA and anaplastic astrocytoma, whereas mutations ofTBC1D19,ESRRA,DIAPH2,COG6, andCBWD3occurred in HGA." (PMID 34430964, 2021).
angioimmunoblastic T-cell lymphoma (1 paper, 2013). A mature T-cell non-Hodgkin lymphoma, characterized by systemic disease and a polymorphous infiltrate involving lymph nodes and extranodal sites. "Finally, Nrp1 is expressed by malignant Tfh-like cells in a severe case of angioimmunoblastic T-cell lymphoma (AITL) associated with elevated terminal B cell differentiation." (PMID 24386482, 2013).
aortic aneurysm (1 paper, 2024). A ruptured aneurysm located in the wall of the proximal portion of the descending aorta proceeding from the arch of the aorta. "The SLC44A2/NRP1/ITGB3 complex is a major regulator of vascular smooth muscle cell phenotypic switching and a target of lenalidomide in aortic aneurysm treatment." (PMID 38916960, 2024). "SLC44A2 interacts with neuropilin-1 (NRP1) to activate transforming growth factor β (TGF-β) signaling in an integrin β3–dependent (ITGB3-dependent) manner, which maintains VSMCs’ contractile phenotype and alleviates aortic aneurysm." (PMID 38916960, 2024).
autism (1 paper, 2025). Persistent deficits in social interaction and communication and interaction as well as a markedly restricted repertoire of activity and interest as well as repetitive patterns of behavior. "Together, the coordinated downregulation of Nrp1, Nrp2, Robo2, and Dpysl3 suggests potential impairment in axon-guidance signaling cascades in autism." (PMID 41150532, 2025).
benign ovarian tumors (1 paper, 2020). "Some studies also reported an increased NRP1 expression in OC with respect to normal ovarian tissue and to benign ovarian tumors." (PMID 31898520, 2020). "Moreover, some previous studies reported NRP1 overexpression in OC with respect to normal ovarian tissue and to benign ovarian tumors, as well as a correlation between higher NRP1 expression and shorter survival time." (PMID 31898520, 2020).
bladder tumor (1 paper, 2021). "The expression of interferon-γ receptor was significantly increased after NRP1 silencing, which is not only used as a therapeutic agent for BC treatment but is activation in bladder tumor cells is required for Bacillus Calmette-Guérin-induced tumor elimination and tumor-specific immune memory." (PMID 34249735, 2021).
Bladder urothelial carcinoma (1 paper, 2025). "Recent studies on Bladder urothelial carcinoma (BC) investigated the functions and mechanisms of NRP1 in BC pathogenesis and progression." (PMID 40277760, 2025). "Recent studies about the NRP1 in apoptosis are reported in Bladder urothelial carcinoma." (PMID 40277760, 2025).
brain glioma (1 paper, 2025). A malignant glioma that involves the brain. "These peptides are particularly valuable for their selective targeting capabilities through interactions with specific receptors on brain glioma tissue, and Neuropilin-1 (NRP-1), an overexpressed receptor on the surface of new blood vessels, could be a promising candidate for targeted drug delivery." (PMID 40019229, 2025).
brain hemorrhage (1 paper, 2012). "We report that inhibition of NRP-1, a co-receptor that enhances VEGFR2 (flk-1) receptor activation, decreases vascular permeability, brain hemorrhage, and mortality in this model of CD8 T cell-initiated BBB disruption." (PMID 22985494, 2012). "This study demonstrates that NRP-1 is a potential therapeutic target in neuro-inflammatory diseases involving BBB disruption and brain hemorrhage." (PMID 22985494, 2012).
cerebral malaria (1 paper, 2023). A sequestration of Plasmodium falciparum in the brain, which can cause coma and/or seizures. "Here, we demonstrate a strong induction of Nrp-1 expression on CD8+ T cells in Plasmodium berghei ANKA (PbA)-infected mice that correlated with neurological deficits of experimental cerebral malaria (ECM)." (PMID 38019895, 2023). "Flow cytometry analyses showed the same activated CD8+ T cell phenotype within the Nrp-1+CD8+ T cell subset as observed in mice with cerebral malaria." (PMID 38019895, 2023). "Given the timing of the accumulation of Nrp-1+CD8+ T cells in the brain, we investigated whether the proportion of Nrp-1+CD8+ T cells in the brain correlates with the severity of cerebral malaria." (PMID 38019895, 2023). "As CD8+ effector T cells do not only play an important role in the development of cerebral malaria, but also in other infectious diseases, we hypothesized that Nrp-1 induction might be a more general mechanism." (PMID 38019895, 2023). "In the brain of PbA-infected C57BL/6 mice, progression of cerebral malaria led to a striking increase in Nrp-1 expression on CD8+ T cells between day 5 and 6: Approximately 40% of CD8+ T cells expressed Nrp-1 (left)." (PMID 38019895, 2023). "In murine cerebral malaria and acute LCMV infection, Nrp-1 expression correlated with disease severity and, strikingly, T cell-specific ablation of Nrp-1 improved the outcome of ECM and ameliorated immunopathology in LCMV-infected mice." (PMID 38019895, 2023). "Here, we demonstrated that cerebral malaria and acute LCMV infection led to induction of Nrp-1 on CD8+ T cells, which is accompanied by a highly activated T cell phenotype and correlates with disease severity and tissue damage." (PMID 38019895, 2023).
cerebrovascular diseases (1 paper, 2023). "A previous study has reported an increased expression of endothelial NRP-1 in the ischemic cerebral hemispheres, which helped to prevent the cellular damage in cerebrovascular diseases." (PMID 37138283, 2023).
chordoma (1 paper, 2021). Chordomas are rare malignant tumors arising from embryonic remnants of the notochord in axial skeleton. "In vitro studies confirmed that NONHSAT114552 acted as ceRNA to regulate NRP1 by directly sponging miR-320d, thus facilitating chordoma cell proliferation and invasion." (PMID 34721048, 2021). "Taken together, our results suggested that NONHSAT114552 promoted chordoma development through regulating miR-320d/NRP1 axis." (PMID 34721048, 2021). "Molecular mechanism analysis demonstrated that NONHSAT114552 can promote the proliferation and invasion of chordoma cells by acting as a ceRNA for miR-320d to regulate NRP1 expression." (PMID 34721048, 2021). "In vivo study demonstrated that NONHSAT114552 moderated chordoma growth by sponging miR-320d to regulating NRP1." (PMID 34721048, 2021). "The rescue assays showed that effects of NONHSAT114552 silencing on chordoma cell biological behaviour were eliminated by miR-320d suppression or NRP1 re-expression." (PMID 34721048, 2021). "Transwell assays manifested that NONHSAT114552 knockdown could significantly inhibit the chordoma cell invasion and such inhibition could be eliminated by re-expressing NRP1." (PMID 34721048, 2021). "Furthermore, invitro and invivo studies indicated that NONHSAT114552 acted as a ceRNA for miR-320d to regulate NRP1 in chordoma tumorigenesis and progression." (PMID 34721048, 2021). "Taken together, NONHSAT114552 moderates chordoma development through regulating NRP1 in vivo." (PMID 34721048, 2021). "Moreover, in-vivo study demonstrated that NONHSAT114552 controlled chordoma growth by sponging miR-320d to regulate NRP1." (PMID 34721048, 2021). "Furthermore, the influences of NONHSAT114552/miR-320d/NRP1 axis on chordoma tumorigenesis were investigated in vivo." (PMID 34721048, 2021). "miR-320d may influence the chordoma progression by directly downregulating the expression of NRP1." (PMID 34721048, 2021).
choroidal neovascularization (1 paper, 2021). An eye disorder described by the growth of new blood vessels that originate from the choroid through a break in the Bruch membrane into the sub–retinal pigment epithelium (sub-RPE) or subretinal space. "Here, we provide evidence that ligands for neuropilin‐1 (NRP1), such as Semaphorin 3A and VEGF‐A, are elevated in the vitreous of patients with AMD at times of active choroidal neovascularization (CNV)." (PMID 33876574, 2021).
chromophobe renal cell carcinoma (1 paper, 2023). Chromophobe renal cell carcinoma is a rare subtype of renal cell carcinoma, originating from the intercalating cells of the collecting ducts and macroscopically manifesting as a well-circumscribed, highly lobulated, solid tumor that is usually diagnosed at an early stage. "Assessment of protein expression of ACE2, TMPRSS2 and NRP1 in clear cell, papillary and chromophobe renal cell carcinoma." (PMID 36595529, 2023).
chronic intestinal pseudo-obstruction (1 paper, 2015). "SMC-specific Nrp1 deficiency resulted in a significant reduction in intestinal length by 6 months, and, by 18 months, in severe constipation, and enlargement of the intestine consistent with chronic intestinal pseudo-obstruction." (PMID 25659123, 2015).
colon adenoma (1 paper, 2011). An adenoma that arises from the colon. "Therefore in order to determine and confirm the expression pattern of NRP-1 in colon adenomas and to establish whether it is associated with butyrate concentration, IHC staining was performed on 16 human polyp samples from the same subjects." (PMID 21401950, 2011).
Crow-Fukase syndrome (1 paper, 2022). "VEGF165 can promote the survival of motor neurons during hypoxia through binding to VEGFR-2 and NRP-1, although elevated levels of VEGF165 have been linked to POEMS syndrome, also known as Crow-Fukase syndrome." (PMID 35303290, 2022).
cutaneous squamous cell carcinoma (1 paper, 2018). "In cutaneous squamous cell carcinoma, NRP1 is expressed in highly differentiated tumors, suggesting that it could function as a reservoir to sequester VEGFA to the epithelial compartment, thereby limiting its bioactivity 39, reducing angiogenesis and tumor progression." (PMID 30027561, 2018).
DiGeorge syndrome (1 paper, 2012). "More importantly, our results demonstrate a requirement for Nrp1 function in endothelium that when compromised leads to DiGeorge syndrome-like defects through mechanisms distinct to those associated with Tbx1 deficiency." (PMID 22396765, 2012). "DiGeorge syndrome in humans is most commonly associated with mutation of the Tbx1 gene, and in mice, the terminal DGS phenotypes of Tie2Cre/Nrp1 and Tbx1 mutants are similar." (PMID 22396765, 2012). "In summation, Tie2Cre/Nrp1 mutants have a high or complete penetrance of cardiac outflow tract, great vessel, pharyngeal organ, and craniofacial defects that collectively typify DiGeorge syndrome in humans and that are also seen with high or complete penetrance in Tbx1 and Vegfa mutant mice." (PMID 22396765, 2012). "We conclude therefore that NRP1 is required as a receptor for VEGF signals that are important in cardiac outflow tract, arch artery, pharyngeal organ, and craniofacial development (i.e., the organs impacted in DiGeorge syndrome)." (PMID 22396765, 2012).
dilatation (1 paper, 2009). "Taken together, our experiments suggest that the large VEGF165 isoform, through binding to VEGFR-2 and NRP1, directly affects the contractile properties of cardiomyocytes, thereby initiating LV dilatation and cardiac disease." (PMID 19357774, 2009).
disc degeneration (1 paper, 2012). "Altogether, these results suggest that Nrp-1 may possess a regulatory role in disc degeneration." (PMID 23284858, 2012).
germinoma (1 paper, 2010). A malignant germ cell tumor arising in the central nervous system. "In the germinoma group, the expression levels of RUNX1T1 and THRB were inversely correlated with expression of miR-146a, and the levels of NRP1, SVIL and PDGFRA were inversely correlated with the expression of miR-142-5p." (PMID 20178649, 2010).
glomerulonephritis (1 paper, 2019). A renal disorder characterized by damage in the glomeruli. "In addition, they observed a higher intensity of staining in patients with focal GMN compared with those with diffuse GN, suggesting that NRP-1 could serve as a biomarker to distinguish both types of glomerulonephritis." (PMID 31533337, 2019).
hearing loss (1 paper, 2017). "There were several pieces of evidence shown here that implicate Nrp1 in age-related hearing loss." (PMID 29059194, 2017).
hemangiosarcoma (1 paper, 2010). "On the other hand, expression of PDGFRβ, CD44, and EPHA2 in hemangiosarcoma cell lines was not predictive for the expression of these proteins in tumor tissues, and a similar trend was observed for Neuropilin 1 and v-Myc." (PMID 21062482, 2010).
immune deficiency (1 paper, 2023). "Similarly, immune deficiency markers, such as CD274 (PD-L1), CTLA4, NRP1, and LAGLS9, were increasingly expressed in the high GRORS tumors." (PMID 37252189, 2023). "On the other hand, RNA-seq data revealed that a variety of immune deficiency markers, such as CD274 (PD-L1), CTLA4, NRP1, and LAGLS9, were increasingly expressed in the high-risk group, which was in line with our previous findings as regards immune suppression of cluster 1 determined by ROGs." (PMID 37252189, 2023).
inflammatory bowel disease (1 paper, 2019). A spectrum of small and large bowel inflammatory diseases of unknown etiology. "Association of surface Sema4a on Tconv cells with Nrp1 on Tregs increased Treg survival and function in vitro and was found to be required for the in vivo suppression of inflammatory bowel disease." (PMID 31120919, 2019).